PPFIA3 (PPFI scaffold protein A3)
Description:
May regulate the disassembly of focal adhesions. May localize receptor-like tyrosine phosphatases type 2A at specific sites on the plasma membrane, possibly regulating their interaction with the extracellular environment and their association with substrates.
Synonyms: KIAA0654; LPNA3; MGC126567; MGC126569; NEDPACH
Tractability: PROTAC: ubiquitination databases record sites on it; its protein half-life has been measured.
Gene: Protein-coding gene on chromosome 19 (49,119,418 to 49,151,027, forward strand). Ensembl gene ENSG00000177380.
Subcellular location: Cytoplasm; Cytoplasmic vesicle, secretory vesicle, acrosome
Pathways (Reactome):
Neuronal System: Acetylcholine Neurotransmitter Release Cycle; Dopamine Neurotransmitter Release Cycle; Glutamate Neurotransmitter Release Cycle; Norepinephrine Neurotransmitter Release Cycle; Receptor-type tyrosine-protein phosphatases; Serotonin Neurotransmitter Release Cycle
Gene Ontology:
Molecular function: protein binding
Biological process: neurotransmitter secretion; regulation of short-term neuronal synaptic plasticity; synapse organization; synaptic vesicle exocytosis
Cellular component: acrosomal vesicle; cytosol; epididymosome; presynaptic active zone; cytoplasm; glutamatergic synapse; presynaptic active zone cytoplasmic component; synapse
Genetic constraint (gnomAD): Loss-of-function variants: 26 observed, 136.73 expected, observed/expected ratio (o/e) 0.19, 90% interval 0.14 to 0.26. The upper end of that interval is the gene's LOEUF score, 0.26, which puts it in group 1 of 6, group 1 being the genes least tolerant of losing a copy. Missense variants: 1,008 observed, 1,553.4 expected, observed/expected ratio (o/e) 0.65, 90% interval 0.62 to 0.68. Synonymous variants: 645 observed, 646.09 expected, observed/expected ratio (o/e) 1, 90% interval 0.94 to 1.07.
Homologues: Orthologues: macaque PPFIA3 (99% identical), chimpanzee PPFIA3 (99% identical), dog PPFIA3 (99% identical), guinea pig PPFIA3 (98% identical), mouse Ppfia3 (98% identical), rat Ppfia3 (98% identical), pig PPFIA3 (97% identical), tropical clawed frog ppfia3 (82% identical), zebrafish ppfia3 (77% identical), Drosophila melanogaster Liprin-alpha (49% identical). Paralogues in human: PPFIA1 (63% identical), PPFIA2 (62% identical), PPFIA4 (61% identical), PPFIBP1 (19% identical), PPFIBP2 (19% identical).
Diseases named in the same sentence as PPFIA3 in open-access papers:
PPFIA3 is named in the same sentence as 6 diseases in open-access papers, as found by Europe PMC text mining. Sharing a sentence is not in itself a finding about the gene and the disease. The quoted sentences say what the papers report.
gastric cancer (5 papers, 2016 to 2023). A primary or metastatic malignant neoplasm involving the stomach. "PPFIA3 is a significant marker of gastric cancer and has independent prognostic value in patients with pancreatic cancer 10-12." (PMID 36605492, 2023). "Serum analysis of methylation of PPFIA3 genes has been suggested as an effective non-invasive detection method of gastric cancer." (PMID 34094943, 2021). "PPFIA3 can be methylated in gastric cancer but is rarely methylated in normal gastric tissues." (PMID 36605492, 2023). "In addition, the methylation of PTPRF-interacting protein alpha 3(PPFIA3) in serum has shown a potential for the detection of gastric cancer." (PMID 32711505, 2020).
depression (1 paper, 2023). "Liprin-alpha involvement in synaptic neuroplasticity is further demonstrated by evidence that interactions between Ppfia3 and AMPA receptors are required for muscarinic receptor-mediated long-term depression." (PMID 37834084, 2023).
prostate carcinoma (1 paper, 2008). A carcinoma that arises from epithelial cells of the prostate gland. "A 5-gene recurrence predictor of prostate cancer contains KLF6, three common ARACNe-based predictions between MYC and KLF6 (FOS, JUNB and ZFP36), and PPFIA3, which is functionally related to another predicted target of KLF6 (PPFIBP2)." (PMID 18190704, 2008).
tumor (3 papers, 2016 to 2023). "Additionally, recent articles have reported that VAV3 (a member of VAV gene family which plays an important role in the process of tumor development and metastasis) and PTPRF-Interacting Protein Alpha-3 (PPFIA3) may associated with the tumorigenesis and development of GC." (PMID 27143812, 2016). "Moreover, when we stratified the TNM stages and analyzed the diagnostic value between those two methods in each stage, we found that detection of OSR2, VAV3, and PPFIA3 hypermethylation showed significantly higher sensitivity than that of serum tumor markers." (PMID 27143812, 2016). "Finally, we wanted to verify whether knockdown of PFKFB3 or ENO2 would abrogate the tumor-promoting effects of PPFIA3." (PMID 34094943, 2021).
cancer (1 paper, 2023). A tumor composed of atypical neoplastic, often pleomorphic cells that invade other tissues. "Materials and methods: In this study, several databases, including Oncomine, UALCAN, and the cancer cell line encyclopedia, were used to compare differences in PPFIA1, PPFIA2, PPFIA3, and PPFIA4 expression between normal colon samples and CRCs." (PMID 36605492, 2023).
PPFIA3 also shares sentences with these, for which no sentence is quoted: sideroblastic anemia (1 paper).